MYCN (MYCN proto-oncogene, bHLH transcription factor)
Diseases named in the same sentence as MYCN in open-access papers (continued):
Sharing a sentence is not in itself a finding about the gene and the disease.
tumor (continued). "Indeed, treatment with CHIR99021 significantly increased EdU incorporation in ALK/MYCN POSTN sgRNA tumor cells." (PMID 38451815, 2024). "IDRFs, high stage of INRGSS, retroperitoneal lymph node metastasis, and vascular encasement were significant risk factors for perioperative complications, yet MYCN amplification and tumor size were not significant risk factors." (PMID 38070095, 2024). "Inhibition of MTHFD1 augments the anti-tumor effect of JQ1 in MYCN-amplified NB." (PMID 38336749, 2024). "Alternatively, tumor microenvironmental features may be required to induce MYCN transcription in vivo." (PMID 38748789, 2024). "MiR-145–5p suppress neuroendocrine differentiation and tumor progression via SOX11/MYCN axis." (PMID 38887275, 2024). "Accordingly, the authors hypothesised that CT-based radiomics features were linked to heterogeneity, and, through that, to patient outcomes including IDRF, tumour differentiation, metastasis, and MYCN amplification status." (PMID 38249081, 2024). "MYCN mRNAs contain a structural element known as an internal ribosome entry segment (IRES) in their 5′ UTRs, responsible for increased translation levels associated with tumor growth and genotoxic stress responses during treatment." (PMID 37975412, 2024). "To further determine whether the combination of STM2457 and VCR represented a more effective and safer therapeutic schedule for MYCN-amplified NB, we assessed its effect on tumor growth in vivo." (PMID 38745192, 2024). "In tumours with MYCN amplification and hence a worse prognosis, the oncogene is able to downregulate the expression of TrkA through binding with the transcription factors SP1 and MYZ1, forming a complex that recruits a histone deacetylase, HDAC1, which induces a repressed chromatin state." (PMID 38542729, 2024). "Together, the novel PP2A activators and pharmaceutically druggable approach in the current study target MYCN degradation, leading to a significant reduction in overall cell viability, proliferation, and migratory potential and a reduction in tumor volume in vivo." (PMID 39594793, 2024). "As MYCN amplification is also associated with the differentiation of NT tumors, more complex gangliosides can be observed in GN and GNB, which are more differentiated tumor entities." (PMID 39449099, 2024). "This may be because primary adrenal NB is more likely to have aberrant DNA structure due to amplification of the MYCN gene, as well as alterations in the tumor microenvironment, resulting in tumors that are more likely to develop distant metastases." (PMID 39363969, 2024). "Our results confirm and add new insights into the non-linear relationship between the MYCN-amplified clone’s reproductive advantage in a tumour, the tumour’s other clones (with other mutations), and its gene expression profile." (PMID 39715281, 2024). "From the clinical observation that ceftriaxone treatment can decrease the volume of unexpected MYCN‐driven RB, we demonstrate that ceftriaxone similarly has antitumoral activities in RB and NB cells and is a potent growth inhibitor of MYCN‐amplified tumor cells." (PMID 37975412, 2024). "The Mycn Type, as the name suggests, includes tumours that harbor amplification of the MYCN gene." (PMID 39217334, 2024). "Although this mechanism has yet to be investigated in HGSC, elevated expression of ALK protein was reported in 28% of HGSC samples (independent of ALK mutation or gene rearrangement), providing one potential mechanism for MYCN up-regulation in the tumor microenvironment." (PMID 38748789, 2024). "Likewise, orthotopic injection into the adrenal gland (n = 3 mice per condition) yielded tumour growths visible by magnetic resonance imaging (MRI) after 5 weeks only when MYCN overexpression was induced by DOX in 17q1qMYCN-grafted animals." (PMID 38702304, 2024).
tumor (continued). "The results of this method in our studies demonstrated the elimination of tumor masses in both high-risk MYCN-amplified and non-amplified tumors as well as in matching pretreatment primary and posttreatment recurrent isolates." (PMID 38214542, 2024). "MYCN amplification is a powerful prognostic factor for advanced stages and rapid tumor progression." (PMID 39049899, 2024). "Among 134 patients whose tumor MYCN status was known, MYCN was amplified in 43 (32%) of them." (PMID 39062971, 2024). "LL and diarrhea were more likely to be associated with larger tumor size, Shimada classification as NB, presence of IDRFs, high stage of INRGSS, high-risk group of INRG, MYCN amplification, retroperitoneal lymph node metastasis, laparotomy surgery, long period of operations, and vascular encasement." (PMID 38070095, 2024). "Furthermore, the combination therapy involving STM2457 and VCR shows enhanced efficacy in preventing tumor progression and suppressing MYCN expressions." (PMID 38745192, 2024). "In support of the later model, we and others have uncovered critical roles of MYC and MYCN in maintaining the genomic stability of tumour cells, e.g., by coordinating transcription with DNA replication and by enabling promoter-proximal double-strand break repair." (PMID 39177021, 2024). "Nevertheless, the MYCN status seems to cluster better than the tumor entity." (PMID 39449099, 2024). "Finally, within spinal ependymomas, a novel tumor type characterized by MYCN amplification has been introduced with the 2021 classification." (PMID 37658995, 2024). "However, the MYCN-induced RB1-proficient phenotype was consistently more immature and less differentiated with faster tumour progression than that of the RB1-deficient." (PMID 37606819, 2024). "The first conclusion of this subsection is that a MYCN-amplified clone with a higher fractional composition in a tumour does not enjoy a reproductive advantage relative to one with a lower fractional composition in another otherwise identical tumour." (PMID 39715281, 2024). "MYCN-amplified tumors, which are composed of a higher proportion of ADRN type cells, are typically associated with “cold” or low T-cell inflammation (TCI) signatures and few tumor-associated T cells." (PMID 39099200, 2024). "Targeting m6A modification by STM2457, a small-molecule inhibitor of METTL3, could downregulate MYCN expression and attenuate tumor proliferation." (PMID 38745192, 2024). "This DDX3X overexpression may sensitize tumor cells to ceftriaxone treatment in addition to MYCN overexpression." (PMID 37975412, 2024). "Among the significantly downregulated genes was MYCN, which is known to show increased expression and plays a central role in many types of cancers, suggesting that epigenetic regulation may affect tumor cells." (PMID 38411140, 2024). "Collectively, ceftriaxone could inhibit translation via targeting DDX3X, and concomitant inhibition of MYCN overexpression by drug treatment resulted in a significant repression of translation in MYCN‐amplified tumor cells." (PMID 37975412, 2024). "Moreover, CNAs potentiate the pro-tumourigenic effects of MYCN and mutant NC cells resemble NB cells in tumours." (PMID 38702304, 2024). "In contrast, high protein levels of both MYCN and Runx1t1 were only observed in tumor samples." (PMID 38992040, 2024). "Finally, MYCN targets the promotor of the gene, Bmi1, resulting in its upregulation, which decreases the expression of the tumour suppressor genes KIF1Bβ and TSLC1 (tumour suppressor in lung cancer-1)." (PMID 38542729, 2024). "As expected, NUDT1 inhibition induced significant cell death in all the tumor cells associated with MYC/MYCN overexpression, whereas those with low MYC/MYCN levels exhibited minimal cell death, underscoring the association between MYC overexpression and NUDT1 dependency." (PMID 38493213, 2024). "In the Polish population, tumor imprints are routinely used to assess MYCN amplification." (PMID 39049899, 2024).
tumor (continued). "Interestingly, when combining used MTX and JQ1 in MYCN-amplified NB, a synergistic anti-tumor effect was found in our study." (PMID 38336749, 2024). "Importantly, CAMKV levels were previously correlated to a worse NB patient survival and its expression is highly associated to that of MYCN or MYC in NB cell lines and primary tumor samples." (PMID 38255303, 2024). "Inhibition of FAK in ALK/MYCN tumor cells increased GSK3β activity." (PMID 38451815, 2024). "Thus, ALKF1174L cooperated with MYCN to reduce apoptosis and accelerate tumor growth in the human stem cell model." (PMID 38451815, 2024). "In cells with CNAs and MYCN overexpression, this orderly reconfiguration of chromatin was severely disrupted in a manner similar to NB cells, providing a plausible mechanism for the link between the observed developmental defects and tumour initiation." (PMID 38702304, 2024). "Therefore, we ectopically expressed MYCN in Daoy cells (Daoy-MYCN) and then inoculated these cells into mouse brains to observe tumor formation and metastasis." (PMID 38689348, 2024). "In tumors with MYCN overexpression, as is the case of NB, interaction with CDK2 appears to be critical for senescence avoidance and immortalization, being associated with worse prognosis and considered a suitable therapeutic target in this tumor type." (PMID 36839989, 2023). "Several key tumor suppressor miRNAs are shown to be repressed by MYCN in the context of MNA." (PMID 38069407, 2023). "In addition to its canonical function as a transcription factor, MYCN transcripts can also mediate oncogenic features as a competing endogenous RNA (ceRNA) for let-7, a family of microRNAs with tumor suppressor functions in various human malignancies." (PMID 37611092, 2023). "A previous study has revealed that MDM2 could upregulate the transcription and translation of MYCN, an essential component to RB cell growth and tumor formation." (PMID 36741966, 2023). "Disrupting the MYCN enhancer regulatory axis and targeting SEs holds promise as therapeutic strategies in NB, offering potential avenues to inhibit oncogenic transcription and inhibit tumor growth." (PMID 38069407, 2023). "However, even with tail vein injection, cohorts of mice receiving Th-MYCN-derived primary NB cells will enable the assessment of tumor responses at multiple clinically relevant tissue sites." (PMID 37569447, 2023). "Moreover, R26IGF2BP1/MYCN substantially elevated tumor burden per animal with 19 tumors observed in 8 animals." (PMID 37246217, 2023). "In this study, we profiled CNAs in the tumor tissue from pediatric cancer, including embryonic tumors, followed by further evaluation of CNAs in 1q, MYCN and 17p in the circulating cell-free DNA (cfDNA) from plasma samples for long-term disease monitoring through liquid biopsy." (PMID 37189699, 2023). "In line with this notion, we found BAP1 knockdown could inhibit MYCN-amplified NB cells proliferation, migration and tumor growth in BE2C and SH-EP Tet21/N cells and in xenograft mice models which support the notion that BAP1 might be an oncogene in NB." (PMID 37543638, 2023). "To establish a platform for the testing of anti-NB activity across a broader range of tumor sites in an immune-competent setting, we developed a transplantation model utilizing primary luciferase-tagged NB cells isolated from tumors arising in Th-MYCN mice." (PMID 37569447, 2023). "Patients are stratified into high-risk (HR) and non-HR categories based on age at diagnosis, tumor stage, histology and genetic factors such as amplification of the MYCN gene." (PMID 37426669, 2023). "Indeed, PP showed efficacy in inhibiting NEPC tumor growth not only in the LASCPC-01 xenograft model characterized by robust MYCN expression but also in TKO mice characterized by a mild degree of MYCN expression." (PMID 38016952, 2023).
tumor (continued). "In our present study, we found that ONC201 treatment could significantly inhibit the protein expression of MYCN in MYCN-amplified NB cells with a promising tumor suppressor effect in xenograft tumors." (PMID 36675163, 2023). "Moreover, genetic deletion or pharmacological inhibition of Syk with R788 promotes immunostimulation, increases CD8+ T cells, and decreases tumor progression in a MYCN-driven mouse model of NB." (PMID 37350973, 2023). "After collecting and processing the data in TCGA-KIRC database, the researchers compared the content of MYCN and other factors in normal kidney tissue and pathological tissue and found CDKN2A and ZBP1 in tumor tissues were up-regulated and MYCN was down-regulated." (PMID 37878133, 2023). "Furthermore, ONC201 treatment significantly decreased MYCN protein expression and suppressed tumor formation with the reactivation of ATRX expression in MYCN-amplified NB-cell-derived xenograft tumors." (PMID 36675163, 2023). "In conclusion, this study revealed that the regrowth of MYCN-amplified tumours post-COJEC is influenced by the infiltration of macrophages to the TME, and inhibiting macrophage recruitment can be a viable follow-up treatment option for post-treatment relapse in high-risk NB." (PMID 37887559, 2023). "Furthermore, BAP1 knockdown inhibits NB tumor cells growth and migration in vitro and in vivo, which can be rescued partially by ectopic expression of MYCN." (PMID 37543638, 2023). "These early lesions proliferated strongly, and MYCN staining confirmed overexpression in the tumor." (PMID 37407554, 2023). "That is, recapitulation of MYCN expression in preclinical models could be vital depending on the specific research question or tumor grade of interest." (PMID 37533331, 2023). "All tumor cell populations showed high expression levels of the human MYCN (hMYCN) reporter gene." (PMID 37407554, 2023). "Taken together, we demonstrated tumor development in the murine OB with early postnatal onset induced by the cooperative effects of Crebbp inactivation and overexpression of exogenous human MYCN." (PMID 37407554, 2023). "Furthermore, MYCN-amplified NB tumours post-treatment were stained with chromogranin A and CD45, which showed the presence of immune cells." (PMID 37887559, 2023). "Additionally, trichostatin A, another HDAC inhibitor, restored the expression of the differentiation protein transglutaminase 2 (TG2), usually repressed by MYCN in NB cells, resulting in reduced tumor volume in the same mouse model." (PMID 38069407, 2023). "Hence, hGFAP-cre::CrebbpFl/Fl::lsl-MYCN tumor cells can be characterized as proliferative, multipotent, and tumorigenic in the forebrain (non-olfactory bulb) microenvironment." (PMID 37407554, 2023). "Notably, consistent with in vitro cellular results and subcutaneous xenograft results, depletion of BAP1 significantly inhibits the growth of implanted tumor cells, but overexpression of MYCN partially rescued BAP1 depletion-mediated cells growth retardation." (PMID 37543638, 2023). "The prognosis of malignant PNTs varies significantly based on patient age, disease stage, and biological factors, including the histological category and grade of tumor differentiation, amplification of the MYCN oncogene, DNA ploidy, and chromosomal aberrations." (PMID 38013377, 2023). "Based on the high expression of CCNB1IP1 in MYCN‐AM NB cells, we hypothesized that an excess of CCNB1IP1 facilitated MYCN‐driven tumour‐promoting functions of NB cells." (PMID 37461251, 2023). "In this situation, TAp63 could be particularly important for reducing tumor aggressiveness by decreasing MYCN transcripts." (PMID 36831211, 2023). "This hypothesis can be supported by the evidence regarding the response of MYCN levels in tumor cells that have been treated with DFMO." (PMID 37206500, 2023).
tumor (continued). "We further validated the crucial role of BAP1 in tumor promotion by regulating MYCN." (PMID 37543638, 2023). "In NB, c-MYC target genes were significantly upregulated in neoplastic tumor clusters obtained from different datasets, while MYCN targets were significantly upregulated in tumor clusters from the 10x sequenced dataset (Fisher Exact Test, one-tail, FDR < 0.05)." (PMID 37760568, 2023). "Given these premises, we investigated whether BGA002 is able to inhibit MYCN expression in another MYCN-driven tumor, SCLC." (PMID 36765949, 2023). "Notably, GD2 expression levels were maintained at levels comparable to that detected on the original primary Th-MYCN tumor through many rounds of in vivo expansion through various recipient strains." (PMID 37569447, 2023). "In NB, MYCN maintains tumor growth by promoting fatty acid uptake." (PMID 37904700, 2023). "Consistently, depletion of BAP1 in MYCN-amplified BE2C and SH-EP Tet21/N cells but not MYCN non-amplified SH-EP Tet21/N+Dox cells, inhibited cell proliferation and migration in vitro and retarded tumor growth in subcutaneous and orthotopic xenograft mice models in a MYCN-dependent manner." (PMID 37543638, 2023). "Moreover, in NB and SCLC, MYCN-amplified tumor cells are more sensitive to PLK1 inhibitor treatment than tumors with normal N-Myc copy numbers." (PMID 36770809, 2023). "Therefore, we decided to study the effects of MYCN overexpression and a simultaneous loss of CREBBP to understand tumor driving mechanisms." (PMID 37407554, 2023). "Moreover, while drug resistance imposes a failure that reversed the initial response to chemotherapy in patients with SCLC, here we have shown that anti-tumor activity of BGA002 against MYCN-related SCLC occurs independently of multidrug resistance." (PMID 36765949, 2023). "MYCN amplification is a widely recognized negative prognostic factor for NB high-risk cases, leading to advanced tumor stage, high aggressiveness, and poor outcome." (PMID 36982482, 2023). "A classical case includes the Aurora kinase inhibitor CCT137690, which inhibits MYCN protein expression leading to chromosomal mislocalization and apoptosis, demonstrating potent anti‐tumour effects in MYCN‐AM NB cell lines as well as in primary tumour models." (PMID 37461251, 2023). "Molecular tumor tissue analysis identified a high-level MYCN amplification." (PMID 35565208, 2022). "In a similar manner, the behavior of an L2 and MS stage tumor is mostly impacted by MYCN status." (PMID 36139583, 2022). "Patients with an extra-abdominal primary tumor, lower-stage tumor, MYCN non-amplified tumor, or low-risk tumor had longer germline telomere lengths than other patients." (PMID 35902621, 2022). "While the INRG identified 7 potential prognostic factors, including age, INRG stage, tumor differentiation grade, histologic subtypes, absence/presence of 11q aberrations, MYCN status, and tumor cell ploidy, and emphasized pretreatment risk stratification based on the clinical criteria." (PMID 35315591, 2022). "Moreover, NB is a specific tumor characterized by transcriptional gene abnormalities and MYCN is the most critical transcription factor (TF)." (PMID 36539767, 2022). "Importantly, this β1 integrin/MYCN relationship is a potential target for stopping tumor progression." (PMID 35574403, 2022). "In NB, we found that oncogenic MYCN drives FA uptake to maintain tumor growth." (PMID 35764645, 2022).